S100A6 (S100 calcium binding protein A6)
Diseases named in the same sentence as S100A6 in open-access papers (continued):
Sharing a sentence is not in itself a finding about the gene and the disease.
pancreatic cancer (continued). "Our demonstration that S100A6 and annexin 2 coimmunoprecipitate with either S100A6 or annexin 2 antibodies, along with their colocalisation within the cytoplasm and membranes of pancreatic cancer cells, suggest that S100A6 may be a significant annexin 2-binding partner in pancreatic cancer cells." (PMID 19724273, 2009). "Other mass spectrometric studies of pancreatic juice have found CEA, S100A6, S100A8, S100A9, and S100P to be differentially regulated between pancreatic cancer and benign conditions." (PMID 30771135, 2019). "In accordance with these findings, depletion of S100A6 resulted in reduction of ANX2 expression and consequently decreased motility of pancreatic cancer cells." (PMID 25407528, 2014). "A number of proteins of the S100 family, including S100A2, S100A4, S100A6, S100A11 and S100P have been shown to be overexpressed in pancreatic cancer." (PMID 19724273, 2009). "To investigate the potential mechanistic relationship between S100A6 and β-catenin in relation to EMT in pancreatic cancer, we transfected stable β-catenin-knockdown Panc-1 cells with a S100A6 overexpression plasmid or a control plasmid, and evaluated the expression of EMT-related markers." (PMID 25799022, 2015). "We show here for the first time that depletion of S100A6 has a profoundly negative effect on the motility of pancreatic cancer cells." (PMID 19724273, 2009). "al. studied the expression pattern of S100A6 as it pertained to clinical outcome in pancreatic cancer and S100A6 expression was a negative prognostic factor." (PMID 19888321, 2009). "Moreover, overexpression of S100A6, S100A10, S100A11, S100A14, and S100A16 may impair the infiltration and cytolytic activity of cytotoxic lymphocytes in pancreatic cancer." (PMID 36982351, 2023). "Whether S100A6 contributes to pancreatic cancer cell motility through interaction with annexin 2 is not yet clear." (PMID 19724273, 2009).
endometriosis (22 papers, 2012 to 2025). The growth of functional endometrial tissue in anatomic sites outside the uterine body. "S100A6 is involved in osteoarthritis, tumors, nervous system disease, endometriosis, cardiovascular disease, and other related diseases." (PMID 38877413, 2024). "Significantly higher levels of mRNA and protein of S100A6 are also characteristic for endometriosis, a benign growth of endometrial tissue outside the uterus." (PMID 36674873, 2023). "In this review, we focus on the molecular mechanisms and potential therapeutic targets of S100A6 in tumors, nervous system diseases, leukemia, endometriosis, cardiovascular disease, osteoarthritis, and other related diseases." (PMID 37509175, 2023). "S100A6 knockdown in ectopic endometrial stromal cells (ESCs) suppressed p38/MAPK activity and inhibited cell viability, migration and invasion, suggesting that S100A6 may contribute to the pathogenesis of endometriosis." (PMID 36674873, 2023). "Moreover, S100A6 is also involved in non-neoplastic diseases, such as Alzheimer’s disease, amyotrophic lateral sclerosis, epilepsy, acute lymphoblastic leukemia, osteoarthritis, and endometriosis." (PMID 38877413, 2024).
gastric cancer (22 papers, 2008 to 2025). A primary or metastatic malignant neoplasm involving the stomach. "To reveal the association among expression of annexin II and S100A6 in gastric cancer, we also studied the expression of S100A6 and, as we expected, S100A6 was up-regulated in gastric cancer tissues compared to normal gastric tissues." (PMID 22681645, 2012). "In stomach cancer, S100A6 overexpression was associated with larger tumor size and deeper invasion." (PMID 36674873, 2023). "Many studies have found the expression level of S100A6 associated closely with the physiological process of some cancer diseases and affect their apoptosis or proliferation activities, such as hepatocellular carcinoma, cervical cancer, and gastric cancer." (PMID 33942537, 2021). "Likewise, increased S100A6 expression and its DNA hypomethylation are associated with poor prognosis in gastric cancer." (PMID 28498804, 2017). "The detection of S100A6 expression levels in gastric cancer tissue and S100A6 detection in serum showed that it has diagnostic and prognostic value and is likely to become a potential therapeutic target." (PMID 37670392, 2023). "For example, serum levels of S100A6 are positively correlated with the progress of four different types of cancer: gastric cancer, non-small cell lung cancer, ovarian cancer and urinary bladder cancer." (PMID 36674873, 2023). "Serum S100A6 level was significantly increased in some solid carcinomas, including gastric carcinoma, bladder carcinoma and ovarian carcinoma." (PMID 35342420, 2022). "Binding of acetylated histone H3 to a promoter in gastric cancer tissue has been seen when there are minor intensities of CpG methylation in the second exon and first intron of the S100A6 gene." (PMID 33117687, 2020). "Lower levels of CpG methylation in the first intron and second exon regions of the S100A6 gene, accompanied by higher levels of acetylated histone H3 binding to the promoter, have been reported in the gastric cancer tissues." (PMID 29379499, 2017). "As an example, S100A6 serum levels were significantly elevated in patients with gastric cancer and correlated with lymph node metastasis or TNM stage as well as overall survival." (PMID 27709523, 2016). "The importance of annexin II and S100A6 up-regulation in gastric cancer is further highlighted by our results that correlate the unfavorable pathologic parameters of tumors with poor patient prognosis." (PMID 22681645, 2012). "Expression of annexin II in gastric cancer was significantly associated with depth of invasion, lymph node metastasis and distant metastasis, TNM stage, high S100A6 expression, and poor prognosis." (PMID 22681645, 2012). "S100A6 protein negatively regulates CacyBP/SIP-mediated inhibition of gastric cancer cell proliferation, partly through effect on β-catenin degradation and transcriptional activation of Tcf/LEF." (PMID 22295074, 2012). "The endogenous expression of S100A6 in gastric cancer cell line MKN45 was first detected by western blot and immunofluorescence staining." (PMID 22295074, 2012). "Protein expressions of annexin II and S100A6 were also examined by immunohistochemistry in 436 clinicopathologically characterized gastric cancer cases." (PMID 22681645, 2012). "Further multivariate analysis suggested that expression of annexin II and S100A6 were independent prognostic indicators for gastric cancer." (PMID 22681645, 2012). "A total of 163 gastric cancer cases had low expression of both annexin II and S100A6, while 158 gastric cancer cases had high expression of both annexin II and S100A6." (PMID 22681645, 2012). "We also examined annexin II and S100A6 expression in gastric cancer specimens and its correlation with annexin II status." (PMID 22681645, 2012). "Moreover, it has been reported that S100A6 overexpression is induced after DNA hypomethylation in gastric cancer." (PMID 33117687, 2020).
gastric cancer (continued). "Among them, S100A4 and S100A6 have been reported to be epigenetically up-regulated in nasopharyngeal and gastric cancer by DNA hypomethylation over their gene promoter regions, while S100A2 and S100A10 down-regulated in head/neck and pituitary cancer by DNA hypermethylation." (PMID 28498804, 2017). "Moreover, increased serum levels of S100A6 were suggested as a novel biomarker for various inflammatory and malignant diseases including lung and gastric cancer." (PMID 27709523, 2016). "Although the cause and exact mechanism of S100A6 secretion into the bloodstream is not fully understood, different studies revealed elevated serum levels of S100A6 in NSCLC, gastric cancer and urothelial carcinoma and suggested its role as a diagnostic and/or prognostic biomarker." (PMID 27709523, 2016). "Similarly, methylated CDH1 predicts a poor prognosis in gastric cancer patients; however, S100A6 is important in the progression and prognosis of gastric cancer, and is upregulated by epigenetic regulation." (PMID 25788990, 2015). "S100A6 protein levels were found to correlate significantly with the prognosis of gastric cancer." (PMID 22681645, 2012). "Annexin II and S100A6 proteins could be useful prognostic marker to predict tumor progression and prognosis in gastric cancer." (PMID 22681645, 2012). "S100A6 protein was detected in 256 of 436 (58.72%) human gastric cancer cases." (PMID 22681645, 2012). "Therefore, the truncated mutant CacyBP/SIP was named CacyBP/SIPΔS100 and provides a useful tool for investigation of the effects of S100A6 on the biological behavior of CacyBP/SIP in gastric cancer cells." (PMID 22295074, 2012). "We found a positive correlation between annexin II and S100A6 expression with gastric cancer invasion and metastasis, suggesting that cells with positive annexin II expression may promote gastric cancer cell invasion and metastasis." (PMID 22681645, 2012). "S100A6 was found to be widely expressed in gastric carcinomas and its expression could contribute to the progression of carcinomas and be useful in predicting the prognosis of gastric cancer." (PMID 22681645, 2012). "Statistical analysis showed that depth of invasion (P = 0.029), lymph node metastasis (P = 0.025), distant metastasis (P = 0.016), TNM stage (P = 0.021), expression of annexin II (P = 0.027) and expression of S100A6 (P = 0.011) were independent prognostic factors in patients with gastric carcinoma." (PMID 22681645, 2012). "Furthermore, according to the TCGA dataset, we found CA1 was enriched in colorectal cancer and stomach cancer; while S100A6 and DDT showed low cancer specificity, especially that S100A6 showed higher expression in urothelial cancer and DDT showed higher expression in liver cancer." (PMID 39850446, 2025). "Before our investigations, S100A6 in MM had never been documented, however, high levels of both annexin A2 and S100A6 have been associated with poor prognosis in gastric cancer, while high serum levels of S100A6 correlated with lymph node metastasis and TNM stage." (PMID 35873564, 2022). "Similarly, the calcium-binding protein S100A6 was highly expressed in gastric cancer lesions and has also been identified by MALDI-MSI as a potential marker for tumour development of Barrett’s adenocarcinoma, known to develop more rapidly than any other gastrointestinal malignancy." (PMID 29194417, 2017). "It is reported that DNA hypomethylation could induce S100A6 overexpression in gastric cancer." (PMID 29379499, 2017). "Moreover, serum S100A6 levels may serve as a potential prognostic biomarker in gastric cancer, and inhibition of S100A6 decreases the metastatic potential of gastric cancer cells." (PMID 25799022, 2015). "Protein levels of annexin II and S100A6 were up-regulated in gastric cancer compared with adjacent non-cancerous tissues." (PMID 22681645, 2012).
gastric cancer (continued). "Calcyclin-binding protein (CacyBP/SIP), a 30 kDa protein identified on the basis of its ability to interact with S100A6 in a Ca2+-dependent manner in Ehrlich ascites tumour (EAT) cells, was previously thought as a multiple-drug resistance (MDR)-related molecule in gastric cancer in our laboratory." (PMID 22295074, 2012). "S100A4, S100A6 and S100A7 were shown to be upregulated in gastric cancer in only one dataset but did not exist in the other two datasets." (PMID 18793447, 2008).
lung carcinoma (14 papers, 2009 to 2025). "Overexpression of S100A6, driven by miR-193a or by HIF-1-α-induced hypermethylation of the S100A6 promoter region, has been linked to the promotion of lung cancer cell proliferation, invasion, migration, and angiogenesis." (PMID 41164170, 2025). "S100A6 was bifacial in lung cancer: it inhibited lung cancer cell growth, but its upregulation predicted a poor prognosis of NSCLC24,25." (PMID 41423496, 2025). "Although two studies assert that S100A6 induces apoptosis in Calu‐6 lung cancer cells and chondrocytes, several others posit its antiapoptotic effect in cardiomyocytes and clear cell renal cell carcinoma." (PMID 39309696, 2024). "MiR-193a was reported to repress the oncogenesis reactions of lung cancer cells by directly targeting S100A6." (PMID 31850060, 2019). "S100A6 signaling through RAGE may be involved in lung cancer pathogenesis, and it is a promising diganostic marker, like S100A2, for early stage NSCLC detection." (PMID 41164170, 2025). "The expressions of S100A6 were different in different subtypes of lung cancer." (PMID 38271114, 2024). "The S100A6 protein, which was found to be an interacting partner of SPRR3 and SPRR1A in KLK6 high group, has been associated with cells motility and tumor metastasis in cervical cancer cells and lung carcinoma." (PMID 34065672, 2021). "Similarly, increased S100A6 expression was associated with a survival benefit for non-small cell lung cancers; S100A6 was demonstrated in 2 lung cancer patients' sera, and in the pleural effusion of one." (PMID 19888321, 2009).
melanoma (13 papers, 1998 to 2025). A malignant, usually aggressive tumor composed of atypical, neoplastic melanocytes. "Subsequent studies showed that increased S100A6 expression is associated with the metastatic potential of human melanoma cell lines and primary melanomas." (PMID 15280928, 2004). "MOF-based hydrogel has also been used to treat melanoma by regulating melanoma prognostic markers (VEGFa and S100A6)." (PMID 39852047, 2025). "For example, S100B is a known marker of melanoma, and some other members of the S100A family, like S100A2 and S100A6, are thought to have a role in the progression of melanoma from normal melanocytes to metastatic disease." (PMID 38892279, 2024). "In our xenograft mouse model of melanoma, S100A6 was also found up-regulated in tumors from RAGE overexpressing WM115 melanoma cells compared to tumors from control WM115 cells." (PMID 33256110, 2020). "S100A6 is overexpressed in Spitz nevi, melanocytic nevi, and melanomas; in fact, tissue analysis of melanoma patients revealed that most melanomas showed positive staining for S100A6." (PMID 33256110, 2020). "An early study revealed a positive correlation between the overexpression of S100A6 and the metastasis of human melanoma cell lines." (PMID 33256110, 2020). "The expression of S100A6 was described in cutaneous and extracutaneous lesion including melanocytic nevi and malignant melanoma." (PMID 33256110, 2020). "Subtypes of the family of S100 proteins may be of some help in distinguish different melanocytic lesions; in a study of 42 SN cases, all of these lesions strongly expressed the S100A6 protein compared with only 33% of 105 melanoma cases." (PMID 35747831, 2022). "Interestingly in osteosarcoma, a trend was observed between decreased metastasis and increased S100A6 staining, contrasting the findings in melanoma and colorectal cancer." (PMID 19724273, 2009). "Moreover, SN may display a diffuse pattern of S100A6 whereas melanoma appears to display a patchy distribution." (PMID 35747831, 2022). "In addition, the expression and staining pattern of S100A6 might be useful in distinguishing different forms of melanoma." (PMID 33256110, 2020). "In analyzing the MeLiM tissue by MALDI MSI, each of the tentatively identified proteins (specifically, MT, S100-A6 and thymosin β-10) could be monitored individually within a single experiment, enabling multiplex signature generation for the improvement of melanoma diagnostics." (PMID 29220390, 2017). "S100 subtypes: S100B, S100P, S100A4, S100A6, and S100A13 are often found in melanoma, with S100P being positive in all melanoma subtypes." (PMID 37504268, 2023). "Indeed, in the context of melanoma xenograft tumors, we showed that overexpression of RAGE resulted in the upregulation of S100A2, S100A4, S100A6, and S100A10, both at the transcript and protein levels." (PMID 37627239, 2023).
colorectal cancer (12 papers, 2008 to 2025). A primary or metastatic malignant neoplasm that affects the colon or rectum. "Top statistically significant hits included ADAMTS5, ATP6V1C2, and S100A6—genes that have been previously identified as biomarkers for colorectal cancer." (PMID 37138315, 2023). "Consequently, we supposed that a series of genes, CTTN, S100A4, S100A6, etc., were potential colorectal cancer metastasis biomarkers." (PMID 36523772, 2022). "In addition, applying HEART on two subpopulations of megakaryocytes, we found several potential cancer biomarkers (CTTN, S100A4, S100A6, UBA52, FAU, and VIM, etc.)associated with colorectal cancer progression and metastasis in literature." (PMID 36523772, 2022). "They found out that S100A6 accumulates in the invasive margin of the colorectal cancer." (PMID 26880885, 2016). "S100A6 overexpression was shown to result in increased phosphorylation (activation) of p38 and ERK1/2 kinases in colorectal cancer cell lines, while S100A6 knockdown corresponded to lower phosphorylation." (PMID 36674873, 2023). "Furthermore, we applied HEART to a single-cell dataset of a colorectal cancer patient and identified several potentially metastasis-related biomarkers, CTTN, S100A4, S100A6, etc." (PMID 36523772, 2022). "Thus, the effect of S100A6 modulation of CacyBP/SIP translocation on the function of tumorigenesis, especially in colorectal cancer, is worthy of future studies." (PMID 29534068, 2018).